KPNB1 (karyopherin subunit beta 1)
Diseases named in the same sentence as KPNB1 in open-access papers (continued):
Sharing a sentence is not in itself a finding about the gene and the disease.
influenza infection (1 paper, 2021). "From MAGMAv1.07b, we identified three significant genes with a primary role in influenza infection: FGFR2, KPNB1 and NUP153." (PMID 33924631, 2021).
neuroblastoma (1 paper, 2013). Neuroblastoma (NB) is the most common solid, extracranial childhood tumor. "According to our previous study, KPNB1 expression was markedly decreased in SK-N-SH human neuroblastoma cell line after Aβ treatment and such reduced KPNB1 expression could be prevented by ME." (PMID 24386444, 2013).
Pain (1 paper, 2023). An unpleasant sensory and emotional experience associated with actual or potential tissue damage, or described in terms of such damage. "The study also found a negative correlation between miR-101 and KPNB1 in the sural nerve biopsies and a reduction in miR-101 relates to the activation of NF-κB signalling in vivo and in vitro, which contributes to the pathogenesis of neuropathic pain." (PMID 37928202, 2023).
pancreatic cancer (1 paper, 2022). "By analysing the TCGA database, we found that the prognosis of PDAC patients with high KPNB1 expression was worse, suggesting that KPNB1 functions as an oncogene in pancreatic cancer." (PMID 35864095, 2022). "Our results demonstrated that PCDH1 promoted p65 nuclear import, which activated the NF-κB pathway in pancreatic cancer cells and tissues, and that this activation was achieved through PCDH1 interaction with KPNB1, a widely studied nuclear transporter." (PMID 35864095, 2022).
Sepsis (1 paper, 2024). Sepsis is defined as life-threatening organ dysfunction caused by a dysregulated host response to infection. "Moreover, the protein expression of KPNB1 in the plasma EVs of patients with sepsis increased significantly compared to that in controls." (PMID 39119837, 2024). "Consequently, elevated levels of EC‐derived EVs and KPNB1 in EVs in the plasma may play a key role in the aberrant migration of PMNs, which may contribute to the development of ARDS in human sepsis." (PMID 39119837, 2024).
cancer (30 papers, 2013 to 2026). A tumor composed of atypical neoplastic, often pleomorphic cells that invade other tissues. "Studies have also found that KPNB1 expression is up-regulated in a number of cancers, and dysregulation of KPNB1 is closely linked to carcinogenesis." (PMID 40370665, 2025). "Karyopherin β1 (KPNB1) participates in the nuclear import of many cancer-associated proteins including DR55–8." (PMID 30742128, 2019). "Collectively, the susceptibility of cancer cells to KPNB1 deficiency-induced apoptosis makes KPNB1 a candidate target for cancer therapy." (PMID 29520102, 2018). "Karyopherin β1 (KPNB1) is an important nuclear receptor that participates in the nuclear import of many cancer-associated proteins, and whose expression is related to tumor progression in multiple cancer types." (PMID 38254206, 2024). "Meanwhile, KPNB1 is also associated with the metastasis of cancer cells." (PMID 35902727, 2022). "KPNB1 could be functioning as one of the key transporters of transcription factors associated with cancer cell migration, invasion and metastasis." (PMID 28427184, 2017). "Moreover, dysregulation of KPNB1 has been linked to several types of cancer." (PMID 35794401, 2022). "As inhibiting KPNB1 resulted in an inhibition of NFkB activity we next investigated whether inhibiting nuclear import affects the expression of NFkB target genes specifically involved in inflammatory signaling associated with cell biology changes in cancer." (PMID 28427184, 2017). "In cells where KPNB1 was inhibited, the transcriptional activities of AP-1 and NFκB, critical for cancer cell biology and the expression of inflammatory target genes, were repressed." (PMID 40370665, 2025). "KPNB1 plays an important role in a variety of cancers, and in this study, we revealed a novel regulatory mechanism of KPNB1 in GBM cells." (PMID 38254206, 2024). "In breast cancer, suppression of KPNB1 inhibited cancer cell proliferation by abrogating the nuclear transport of Her2." (PMID 38254206, 2024). "Using LC-MS/MS proteomics, we found a novel interaction between TMCO1 and nuclear transport proteins, including KPNB1 and IPO7, which are associated with several cancers." (PMID 39353922, 2024). "KPNB1 is a nuclear receptor that is highly expressed in a variety of cancers and promotes tumor progression." (PMID 38254206, 2024). "KPNB1, a 17q SRG and oncogene, over-expressed in Group 3γ MBs, encodes a protein over-expressed in various cancers." (PMID 39062749, 2024). "KPNB1 inhibitors have been reported to be effective in inhibiting the proliferation of cancer cells." (PMID 39062749, 2024). "Recent evidence has highlighted the importance of cancer-specific alterations in KPNA subtypes in cancer biology, as well as the benefits of targeting KPNB1 for cancer therapy." (PMID 37623213, 2023). "We previously reported that KPNB1 inhibition increases cytotoxicity in various cancer cells, including HNSCC cells." (PMID 37623213, 2023). "The nuclear import receptor karyopherin β1 (KPNB1), a member of the Karyopherin protein family, is reported to be overexpressed in various cancers and promote carcinogenesis." (PMID 35902727, 2022). "The KPNB1 plays crucial roles in mitotic and chromosomal integrity, influencing the biology of the cancer cell." (PMID 35202347, 2022). "To investigate the underlying mechanism, we unexpectedly found that PD-L1 translocated into the nucleus of cancer cells which was facilitated through the binding of Karyopherin β1 (KPNB1)." (PMID 33139930, 2021). "In breast cancer, suppression of KPNB1 inhibited cancer cell proliferation by abrogating nuclear transport of Her2." (PMID 33139930, 2021). "Inhibition of KPNB1 and NUPR1 binding was associated with a synergistic anticancer effect (up to 19.6-fold) in various cancer cell lines." (PMID 33801927, 2021).
cancer (continued). "Previously, we reported that (E)-N-(5-benzylthiazol-2-yl)-3-(furan-2-yl) acrylamide (aminothiazole, ATZ-502) showed cytotoxic effects in several cancer cells by blocking the function of KPNB1 with pSTAT3, STAT3, EGFR, and ErbB2." (PMID 33801927, 2021). "Alternatively, miR-101 can play a role macrophage expression via activating the NF-KB signally as a result of the upregulation of the KPNB1 transport protein which is commonly reported in many cancers including HCC." (PMID 33995383, 2021). "We first profiled the clinical status of KPNB1 in HNSCC by re-analyzing data from The Cancer Genome Atlas (TCGA) cohorts via Cancer RNA-Seq Nexus or cBioportal for Cancer Genomics (see Section 4.13 for URLs)." (PMID 32276424, 2020). "Since ionizing radiation is known to increase PD-L1 expression of cancer cells, the authors then investigated the involvement of KPNB1 in the upregulation of cell surface PD-L1 expression on irradiated HNSCC cells." (PMID 32276424, 2020). "It was reported that KPNB1 knockdown primed cancer cells to TRAIL-induced apoptosis by upregulating cell surface DR58." (PMID 30742128, 2019). "Karyopherin β1 (KPNB1) inhibition in cancer cells has been reported to abrogate the nuclear import of TRAIL receptor DR5 and facilitate its localization on the cell surface ready for TRAIL stimulation." (PMID 30742128, 2019). "Inhibitors against KPNB1 and Exportin-1, a nuclear export factor of the karyopherin superfamily, have been tested in different cancers in clinical trials." (PMID 29580221, 2018). "Cancer cells have been found to require KPNB1 for their proliferation although the exact mechanism of action for this requirement is not fully understood." (PMID 28427184, 2017). "In this study, we investigated the requirement of KPNB1 expression and activity for cancer cell migration and invasion." (PMID 28427184, 2017). "Our data provides evidence that supports Darnell's proposal, showing that inhibiting KPNB1 affects AP-1 and NFkB transcriptional activities required for cancer cell biology." (PMID 28427184, 2017). "Our study provides further evidence that inhibiting KPNB1 has anti-cancer effects and shows promise as a chemotherapeutic target." (PMID 28427184, 2017). "Together these results provide further evidence for the role of KPNB1 in cancer cell biological processes such as migration and invasion." (PMID 28427184, 2017). "Previous reports have demonstrated KPNA2 overexpression in various tumors cells in vitro and in vivo; elevated KPNA2 and KPNB1 expression in cancer cells correlates with altered transcriptional regulation associated with deregulated E2F/Rb activities." (PMID 24098495, 2013). "In summary, various reports suggest that the KPNB1 protein may be a potential therapeutic target in cancers." (PMID 39062749, 2024). "Many researchers have demonstrated the important role of KPNB1 in cancer development." (PMID 35902727, 2022). "Therefore, it would be interesting to investigate the role of STAT1 and STAT2 as well as KPNA1 in radiation-increased KPNB1-mediated IRF1 expression in these cancers." (PMID 34069326, 2021). "However, there was the issue that KPNB1 inhibition exerts cytotoxicity against not only cancer cells but also normal cells." (PMID 34069326, 2021). "KPNB1 is often reported as upregulated in many cancers including HCC." (PMID 33995383, 2021). "Moreover, KPNB1 participates in regulating the cell cycle, which is essential for cancer cell proliferation." (PMID 33139930, 2021). "KPNB1 proteins were the major nuclear receptor proteins in the cell, and proliferating cancer cells might regulate the expression of nuclear cytoplasmic transporter KPNB1 protein in varying degrees to maintain increased nuclear transporter." (PMID 32175564, 2020). "Depletion of KPNB1 induces mitotic arrest and apoptosis in cancer cells, but the underlying mechanism is not clearly elucidated." (PMID 29520102, 2018).
cancer (continued). "Consistently, upregulation of KPNB1 expression has been observed in various cancers." (PMID 29520102, 2018). "Given that existing KPNB1 inhibitors are not that efficacious, combining lysosome or proteasome inhibitors may improve the efficacy and selectivity of KPNB1 inhibitors in cancer treatment." (PMID 29520102, 2018). "In our study we have shown that inhibiting KPNB1 reduced migration and invasion of cancer cells." (PMID 28427184, 2017). "Nuclear import inhibition through KPNB1 has also previously been shown in our laboratory and by others to have anti-cancer potential by inhibiting cancer cell proliferation and inducing cell death by apoptosis in vitro as well as inhibiting tumour growth in vivo." (PMID 28427184, 2017). "The data suggests that suppressed NFkB and AP-1 signaling following KPNB1 inhibition may together contribute to the inhibitory effects on cancer cell biology." (PMID 28427184, 2017). "As both NFkB and AP-1 require access to the nucleus in order to be functional we hypothesized that inhibiting nuclear import via KPNB1 may lead to their inactivity and ultimately various downstream effects on cancer cell biology." (PMID 28427184, 2017). "Little is known about the role of KPNB1 in other cancer phenotypes such as migration and invasion." (PMID 28427184, 2017). "Additionally, it was established that circ-PITX1 induced cancer in GBM through targeting the miR-584-5p/KPNB1 axis, implying that circ-PITX1/miR-584-5p/KPNB1 could be used as a diagnostic marker for GBM patients." (PMID 35883576, 2022). "This led us to question whether other cancer phenotypes are also dependent on KPNB1." (PMID 28427184, 2017). "Inhibition of importin subunit KPNB1 by IPZ hindered ARID1B nuclear translocation, potentially disrupting SWI/SNF function in cancer cells." (PMID 40671262, 2025). "To better understand the cellular functions of these prioritized RBPs (TFRC, KPNB1, PUF60, NSF, and SF3A3) in cancer, we next interrogated the HumanNet v2." (PMID 35453681, 2022). "These putative BC progressor RBPs (PUF60, TFRC, KPNB1, NSF, and SF3A3) were integrated into a disease gene network to shed light on their molecular and cellular functions in cancer." (PMID 35453681, 2022). "KPNB1 transports DR5 into the nucleus, while knocking down KPNB1 restores DR5 protein level on the cell surface and TRAIL sensitivity of cancer cells." (PMID 30742128, 2019). "Combination of KPNB1 inhibitor and TRAIL along with the lysosome inhibitor uncoupling pro-survival autophagy has potential in cancer treatment." (PMID 30742128, 2019). "The inhibition of KPNB1 by both siRNA and INI-43 significantly interfered with both HeLa and SiHa cancer cell invasion." (PMID 28427184, 2017). "In this study we investigated the effects of inhibiting KPNB1 using siRNA and a novel small molecule, INI-43, on cancer cell migration and invasion as well as NFkB and AP-1 transcriptional function." (PMID 28427184, 2017). "Given the marked downregulation of NLGN3 following KPNB1 knockdown, and the previously reported roles of NLGN3 in various cancers, especially in nervous system tumors, we hypothesized that KPNB1 regulated GBM progression through NLGN3." (PMID 38254206, 2024). "Overexpression in five of the nine tissue types observed in our heatmaps for KPNB1 and STAT3 may be due to having identified four additional cancer types as significant comorbidities." (PMID 33924631, 2021).
cancer (continued). "Inhibition of the KPNB1 and NUPR1 interaction may constitute a new cancer therapeutic approach that can increase the drug efficacy while reducing the side effects." (PMID 33801927, 2021). "Thus, while importance of cancer-specific alteration of KPNA subtype in cancer biology is recognized, therapeutic benefits from blocking KPNB1, the master nuclear transport receptor mediating all KPNA subtypes, remains to be investigated further." (PMID 32276424, 2020). "Given that most cancers, including GBM, demonstrate a hyper-dependency on nuclear transport, a selective inhibition of RAN/KPNB1 activity by importazole may represent an innovative and effective treatment for GBM." (PMID 30671385, 2018). "Simultaneous PP2A activation and importin inhibition reduces nuclear levels of proteins that drive cancer progression and therapeutic resistance such as JUN, YAP, MYC, androgen receptor, hnRNPA1, and NF-κB under conditions where compounds that target PP2A or KPNB1 individually are inactive." (PMID 40588551, 2025). "However, whether p65 nuclear import mediates the pro-oncogenic function of KPNB1 in these cancers has not been validated." (PMID 29520102, 2018).
tumor (19 papers, 2015 to 2025). "In colorectal cancer, KPNB1 deficiency suppressed tumour cell growth and metastasis by reducing MET expression." (PMID 33139930, 2021). "Overexpression of KPNB1 has been implicated in many tumor types and is associated with poor survival in patients with GBM gastric cancer, and B cell lymphoma." (PMID 33488950, 2020). "Overall, these data indicated that the USP7/KPNB1/YBX1/NLGN3 axis actively regulated tumor progression in GBM." (PMID 38254206, 2024). "We found that the knockdown of KPNB1 inhibited tumor growth and prolonged the overall survival of mice." (PMID 38254206, 2024). "Meanwhile, KPNB1 expression in tumor tissues was upregulated by KPNB1-overexpressed cells injection, whereas KPNB1-silenced cells injection significantly downregulated its expression." (PMID 35902727, 2022). "Inhibiting KPNB1 expression can significantly reduce the proliferative and migratory ability of tumour cells and induce apoptosis." (PMID 35864095, 2022). "Knockdown of KPNB1 reduced cell proliferation, tumor growth, and the number of tumor nodules in mice." (PMID 33488950, 2020). "TCGA RNA-seq data of the HNSCC cohort revealed that the expression level of KPNB1 in tumor tissue was significantly higher than that of normal tissue." (PMID 32276424, 2020). "Our research group has also previously shown that inhibiting KPNB1 using INI-43 reduced tumour growth in a mouse model." (PMID 28427184, 2017). "To confirm the depletion of EZH2 in MPNST xenograft tumors by DZNep treatment in vivo, we conducted Western blot analyses of EZH2 and KPNB1 protein expression in two xenograft tumor samples randomly selected from each group." (PMID 25890085, 2015). "Taken together, these results suggested a tumor-promoting function of KPNB1 in GBM." (PMID 38254206, 2024). "The regulatory mechanism of KPNB1 ubiquitination and deubiquitination in tumor cells remains unclear." (PMID 38254206, 2024). "Furthermore, relative protein levels of cyclin E and cyclin D1 in tumor tissues were inhibited by KPNB1 silencing but enhanced by KPNB1 overexpression." (PMID 35902727, 2022). "Altogether, our study elucidates the tumor-promoting function of KPNB1 through upregulating G3BP1." (PMID 35902727, 2022). "Data showed that DZNep decreased the EZH2 and KPNB1 protein levels of tumor samples." (PMID 25890085, 2015). "Given that PD-L1 is a critical mediator of immune escape and its nuclear translocation enhances immune evasion in tumor cells, we investigated whether KPNB1, a nuclear transport factor, directly regulates PD-L1 nuclear translocation in radiation-resistant NSCLC cells." (PMID 40109769, 2025). "Moreover, KPNB1 is upregulated in various cancer tissues and contributes to tumor progression." (PMID 39414762, 2024). "Importantly, silencing of KPNB1 slowed the tumor development induced by TMEM209 (n = 6)." (PMID 39414762, 2024). "In addition, the presence of KPNB1 is related with tumour progression." (PMID 33139930, 2021). "Pharmacological inhibition of KPNB1 blocked ARID1B translocation from the cytosol to the nucleus, impeding tumor growth." (PMID 40671262, 2025). "Immunoblot and immunohistochemical analyses showed that DZNep downregulated EZH2/KPNB1 signaling in vivo, thereby inhibiting MPNST tumor cell proliferation, and induced cell death." (PMID 25890085, 2015). "Together, these results suggested that DZNep inhibited the EZH2/KPNB1 signaling pathway and MPNST xenograft tumor growth in mice." (PMID 25890085, 2015). "Consequently, nuclear deprivation of ASCL1 and NEUROD1 via KPNB1 inhibition led to impaired growth of SCLC-A and SCLC-N tumor cells in vitro and tumor shrinkage of ASCL1-driven xenografts in vivo." (PMID 38395864, 2024). "Clinical NB cases with up‐regulation of KPNB1, CNBP, SMARCC1, SMARCA4 or down‐regulation of SMARCC2 have poor survival and prognosis, indicating KPNB1/CNBP/SMARCC2 axis as a valuable target for therapeutics of tumours." (PMID 37186134, 2023).
tumor (continued). "This work broadens current literature regarding the functions of SWI/SNF subunits in controlling ribosome biogenesis, and suggests that KPNB1/CNBP/SMARCC2 axis‐mediated ribosome biogenesis and M2 macrophage polarization is a valuable therapeutic target for tumours." (PMID 37186134, 2023). "Because of the importance of EZH2-regulated miR-30d expression that modulates KPNB1 in MPNST cell survival and apoptosis in vitro and in vivo, pharmacological inhibition of EZH2 represents a promising therapeutic approach for this tumor type." (PMID 25890085, 2015). "We analyzed HGSOC patient data for CAS, KPNB1, and KPNB2 expression in the Cancer Genome Atlas (TCGA) based on copy number alteration (CNAs, n = 579), gene expression (RNA Seq V2 RSEM z-scores, n = 308), and protein levels (Clinical Proteomic Tumor Analysis Consortium z-scores, n = 174)." (PMID 35013112, 2022).